PGBD4 (piggyBac transposable element derived 4)
Synonyms: FLJ32638; FLJ37497
Tractability: No criterion of Open Targets' tractability assessment is met for any kind of drug.
Gene: Protein-coding gene on chromosome 15 (34,102,083 to 34,108,686, forward strand). Ensembl gene ENSG00000182405.
Subcellular location (Human Protein Atlas): Nucleoplasm; Centrosome
Genetic constraint (gnomAD): Loss-of-function variants: 3 observed, 1.7 expected, observed/expected ratio (o/e) 1.76, 90% interval 0.62 to 1.94. That is too few expected variants to judge how well the gene tolerates losing a copy. Missense variants: 624 observed, 760.73 expected, observed/expected ratio (o/e) 0.82, 90% interval 0.77 to 0.88. Synonymous variants: 253 observed, 283.58 expected, observed/expected ratio (o/e) 0.89, 90% interval 0.8 to 0.99.
Homologues: Orthologues: chimpanzee PGBD4 (99% identical), macaque PGBD4 (97% identical), tropical clawed frog TxpB_Uribo2 (33% identical), tropical clawed frog TxpB_Kobuta (30% identical).